CDH11 (cadherin 11)
Diseases named in the same sentence as CDH11 in open-access papers (continued):
Sharing a sentence is not in itself a finding about the gene and the disease.
sarcoma (4 papers, 2014 to 2023). A usually aggressive malignant neoplasm of the soft tissue or bone. "Medium expression level of CDH11 was observed in sarcoma (n = 2, M.S. = 171), seminoma (n = 4, M.S. = 164), lymphoma (n = 15, M.S. = 145), teratoma (n = 3, M.S. = 114) and carcinoma (n = 56, M.S. = 110)." (PMID 37558205, 2023). "We selected CCND1, MTA1, STEAP1, CDH2, CDH11, and CDT2 genes that are known to be involved in metastatic spread in several sarcoma subtypes, and their abnormal expression in tumors correlates specifically with poor prognosis in ES patients." (PMID 25008066, 2014). "Calpain-6 may also regulate the Hippo pathway and YAP transcriptional activity by modulating cell-cell interactions in sarcoma SCs because the suppression of calpain-6 with shRNA affected the expression of different genes coding cadherins such as CDH2 and CDH11." (PMID 36153320, 2022).
triple-negative breast carcinoma (4 papers, 2013 to 2023). An invasive breast carcinoma which is negative for expression of estrogen receptor (ER), progesterone receptor (PR), and human epidermal growth factor receptor 2 (HER2). "This is also corroboratory of our recently published work wherein we suggested a correlation between high CDH11 Expression and the poor overall survival rates in patients with basal-like and triple negative breast cancer based on big data analysis." (PMID 31248373, 2019). "We herein provide a basis for further exploration of CDH11 as a putative candidate for targeted therapy in triple negative breast cancer." (PMID 30691241, 2019).
Anxiety (3 papers, 2016 to 2022). Intense feelings of nervousness, tension, or panic often arise in response to interpersonal stresses. "Cdh11 KO mice show reduced anxiety levels and enhanced context-dependent freezing." (PMID 31046797, 2019). "Interestingly, Cdh11-deficient mice revealed enhanced LTP in the CA1 region of the hippocampus and mice show reduced fear- or anxiety-related behavior suggesting that CDH11 might restrict synaptic plasticity and efficacy." (PMID 27909399, 2016). "Behavioral changes that we have observed in Cdh11-null mice, including reduced anxiety, increased repetitive behavior, and reduced sociability, are highly consistent with the non-syndromic ASD case with partial deletion of CDH11." (PMID 34523068, 2022).
autism (3 papers, 2019 to 2022). Persistent deficits in social interaction and communication and interaction as well as a markedly restricted repertoire of activity and interest as well as repetitive patterns of behavior. "Multiple genes have been implicated in autism, including the cadherin superfamily of adhesion molecules, cadherin-8 and cadherin-11." (PMID 34135003, 2021). "The variants in the CDH8 and CDH11 genes identified in individuals with autism are predicted to cause loss of function." (PMID 34135003, 2021). "The classical Type II cadherins cadherin-8 (Cdh8, CDH8) and cadherin-11 (Cdh11, CDH11) have been implicated as autism risk gene candidates." (PMID 34135003, 2021). "We focused our study on the classical Type II cadherins cadherin-8 (Cdh8, CDH8) and cadherin-11 (Cdh11, CDH11) as these specific cadherins have been identified as autism risk genes in a genome-wide association study and by whole exome sequencing." (PMID 34135003, 2021). "Our findings suggest that CDH11 is significantly co-expressed with hcASDs and that its mutations may have a causal effect on autism traits." (PMID 34523068, 2022). "We found downregulation of CDH11 in autism-specific NPCs, which could mimic a loss-of-function phenotype." (PMID 34135003, 2021). "The significant downregulation of CDH11 in autism-specific NPCs prompted us to use the Cdh11 KO mice as a model system to examine potential pathologic phenotypes during neural circuit development and their underlying mechanisms in autism." (PMID 34135003, 2021). "Together, the data suggest that depletion of cadherin-11 causes altered neural circuit development that may drive aspects of autism pathophysiology." (PMID 34135003, 2021). "Our study not only describes a detailed characterization of the autism-risk genes CDH8 and CDH11, but also provides insights into novel functions of cadherin-11 in neural circuit development that may potentially be implicated in the etiology of autism." (PMID 34135003, 2021). "In addition, other studies have identified rare mutations and SNP variants in CDH8 and CDH11 genes, respectively, in individuals with autism." (PMID 34135003, 2021). "CDH8 and CDH11 have been identified as autism-risk candidate genes." (PMID 34135003, 2021). "The segregated expression patterns of Cdh9 and Cdh11 implies that the two genes may contribute to the determination of sub-regions of autism-associated areas in the CB." (PMID 31046797, 2019). "Impaired neuronal connectivity has been suggested to represent a risk factor contributing to etiology of autism, which prompted us to investigate the involvement of cadherin-8 and cadherin-11 in autism." (PMID 34135003, 2021). "In this study, we first evaluated the potential roles of the autism candidate risk genes CDH8 and CDH11 by systematically investigating their expression and localization in mouse tissue." (PMID 34135003, 2021). "Together, these results show that both cadherin-8 and cadherin-11 levels are altered in cells derived from individuals with autism that mimic early stages of neural circuit development." (PMID 34135003, 2021). "The Cdh11 KO mouse has been previously shown to exhibit behaviors that are similar to autism phenotypes." (PMID 34135003, 2021). "We used Cdh11 knock-out (KO) mice of both sexes to analyze the function of cadherin-11, which could help explain phenotypes observed in autism." (PMID 34135003, 2021). "In fact, none of the individuals with autism tested in this study harbor damaging mutations in the CDH8 or CDH11 genes." (PMID 34135003, 2021). "Thus, the reduced migration ability of the autism-specific neurons may stem from the decreased CDH11 expression that we observed in these autism lines." (PMID 34135003, 2021). "In conclusion, our study shows that cadherin-11 plays an important role in regulating dendritic morphology and synaptic function of excitatory neurons, and that altered expression of cadherin-11 may contribute in part to phenotypes observed in autism." (PMID 34135003, 2021).
autism (continued). "Together, these results strongly suggest that cadherin-11 is involved in regulating the development of neuronal circuitry and that alterations in the expression levels of cadherin-11 may contribute to the etiology of autism." (PMID 34135003, 2021). "The levels of cadherin-8 and cadherin-11 in human induced pluripotent stem cell (iPSC)-derived cortical neural precursor cells and cortical organoids of autistic individuals are both altered, strengthening that these two cadherins may be involved in autism etiology." (PMID 34135003, 2021). "Induced pluripotent stem cell (iPSC)-derived cortical neural precursor cells (NPCs) and cortical organoids generated from individuals with autism showed upregulated CDH8 expression levels, but downregulated CDH11." (PMID 34135003, 2021). "We found that homozygous, but not heterozygous Cdh11-null mice displayed autism-like behavioral deficits." (PMID 34523068, 2022). "Consistent with this prediction, behavioral studies showed that Cdh11-null mice, but not Cdh9-null mice, have multiple autism-like behavioral alterations." (PMID 34523068, 2022). "The autism cases investigated in this study did not carry any genetic alterations in CDH8 and CDH11 genes, and yet, they exhibited changes in protein levels of these two cadherins, further strengthening the hypothesis that cadherin signaling may represent an important pathway affected in autism." (PMID 34135003, 2021).
bladder cancer (3 papers, 2019 to 2025). "CDH11 inhibition can suppress mitochondrial respiration in advanced bladder cancer cells and xenograft tumor progression." (PMID 41263259, 2025). "The results revealed that CDH11 is involved in bladder cancer progression." (PMID 41263259, 2025).
Elsahy-Waters syndrome (3 papers, 2020 to 2023). "Mutations in CDH11 are associated with Elsahy Waters syndrome and affected individuals show an inter- and intrafamilial variability regarding the presence of mixed hearing loss." (PMID 35573665, 2022). "The physiological relationship between these two diseases may be traced to generalized hypotonia and share some similarities with the Elsahy-Waters Syndrome, a rare genetic disease that arise from (mostly biallelic) mutations in the cadherin-11 gene." (PMID 32982776, 2020). "EWS, also known as brachioskeletogenital syndrome (BSGS), is an ultrarare AR syndrome caused by mutations in cadherin-11 (CDH11)." (PMID 37818127, 2023).
esophageal cancer (3 papers, 2023 to 2024). A primary or metastatic malignant neoplasm involving the esophagus. "CDH11 has been identified as a potential therapeutic target with existing drugs available, highlighting its clinical relevance in managing T-DM1-resistant esophageal cancer." (PMID 39309859, 2024).
glioma (3 papers, 2010 to 2014). A benign or malignant brain and spinal cord tumor that arises from glial cells (astrocytes, oligodendrocytes, ependymal cells). "We analyzed survival data from tumor gene expression databases (NCI Rembrandt, Oncomine) and found that increased CDH11 expression predicts reduced survival in glioma patients." (PMID 23951053, 2013). "We also found that GBMs have higher expression of CDH11 than mixed gliomas and oligodendroglial tumors." (PMID 23951053, 2013). "Because conventionally cultured cell lines are more easily manipulated, a panel of nineteen conventionally cultured glioma cell lines was screened by Western blot for the presence of E-cadherin, N-cadherin, cadherin-11, β-catenin, and p120 catenin." (PMID 21060868, 2010). "Previous studies show that celecoxib preferentially inhibits the growth of xenografts of cells we now know to be CDH11 expressors such as MDA-231 cells and gliomas." (PMID 24681547, 2014). "In addition celecoxib induces apoptosis in CDH11 positive synovial fibroblasts in a COX-2 independent manner and DMC inhibits glioma growth in animals." (PMID 24681547, 2014).
leukemia (3 papers, 2018 to 2025). A malignant (clonal) hematologic disorder, involving hematopoietic stem cells and characterized by the presence of primitive or atypical myeloid or lymphoid cells in the bone marrow and the blood. "Other genes like ZNF292, PRDM1, and CDH11 demonstrated promoter active demethylation and were previously linked to different leukemia types, where PRDM1 and CDH11 were reported to be frequently epigenetically silenced in these tumors." (PMID 41516186, 2025). "Next, we performed WES of five Sca1‐Lmo2 + nu/nu mice with leukemia and observed 14 somatic alterations (SNVs) in Cdh11 (1/5), Cd1d1 (2/5), Sept6 (2/5), and Hspa1l (1/5; Table EV1)." (PMID 29880602, 2018).
liver disease (3 papers, 2017 to 2025). "By targeting CDH11 or ITGβ1 specifically in mesenchyme, we provide proof of the concept that assembloid cells can be used as platform for mechanistic discovery and to investigate cell-autonomous mechanisms in liver disease." (PMID 40441268, 2025). "Thus, it can be concluded that nicotinamide may affect liver inflammation by regulating the gene expression of MARS1, CDH11 and their related signal pathways, thereby preventing the occurrence of liver diseases." (PMID 37233635, 2023).
lung adenocarcinoma (3 papers, 2013 to 2024). A carcinoma that arises from the lung and is characterized by the presence of malignant glandular epithelial cells. "The results obtained in the present study showed that KIF14 might regulate cell migration and adhesion through associations with CDH11 and MCAM; this increase in the membrane localization of CDH11 in lung adenocarcinoma cell lines is a novel finding with regard to the function of KIF14." (PMID 23626713, 2013). "In lung adenocarcinoma, KIF11 recruits CDH11 to the cell membrane and is known to bind to CDH11; CDH11 is a known outer membrane protein and contributes to cell metastasis." (PMID 39409999, 2024).
mastitis (3 papers, 2020 to 2022). Inflammation of breast tissue during lactation or postpartum due to an obstructed duct or infection. "Specifically, the highly associated CDH11 gene belonging to this module has been identified in the development of mastitis and growth of mammary glands in dairy animals." (PMID 34946969, 2021). "The CDH11 gene is involved in mastitis development and mammary gland growth in lactating cattle." (PMID 36230283, 2022). "Additionally, some of the highly connected genes belonging to this module have been found by others to be related to mastitis development, immune response or mammary gland development including FYN, CDH11, CAV1, F11R, ZEB1, ERBB2, and ERBB3." (PMID 32754201, 2020).
oral squamous cell carcinoma (3 papers, 2021 to 2024). "Based on the Whole-genome sequencing of mouse oral squamous cell carcinoma model, CDH11 was found to be a high-frequency mutation gene in OSCC, which suggests its importance in the progression of OSCC." (PMID 37013637, 2023). "CDH11 and CD44 are over-expressed in oral squamous cell carcinoma (OSCC) and involved in OSCC metastasis." (PMID 33737587, 2021).
renal carcinoma (3 papers, 2014 to 2019). A carcinoma arising from the epithelium of the renal parenchyma or the renal pelvis. "This is consistent with the findings from prostate and renal cancers, wherein tissue samples from the bone metastatic site exhibited higher expression levels of the CDH11 protein than observed in primary tumor or adjacent normal tissue." (PMID 30691241, 2019). "In prostate and renal cancers, CDH11 plays an important role in distant bone metastasis." (PMID 30691241, 2019). "Immuno-histochemical analysis of cadherin-11 expression in an array of human renal carcinoma tissues demonstrated that the number of human specimens with positive cadherin-11 activity was significantly higher in tumors that metastasized to bone than in the primary tumors themselves." (PMID 27338367, 2016). "Immunohistochemical analysis of cadherin-11 expression in a human renal carcinoma tissue array showed that the number of human specimens with positive cadherin-11 activity was significantly higher in tumors that metastasized to bone than that in primary tumors." (PMID 24587095, 2014).
synovitis (3 papers, 2016 to 2020). Inflammation of a synovial membrane. "Our previous study demonstrated that Cadherin-11 expression in FLS was positively related to the degree of synovitis." (PMID 31829201, 2019).
brain tumor (2 papers, 2010 to 2013). "Together, these expression data are consistent with the idea that CDH11 expression levels are increased in brain tumors and correlate with brain tumor grade and suggest a function for CDH11 in brain tumor aggressiveness." (PMID 23951053, 2013). "CDH11 expression is elevated in human brain tumors, correlating with higher tumor grade and decreased patient survival." (PMID 23951053, 2013). "Most of the lines expressed N-cadherin and/or cadherin-11, which are frequently found in brain tumors and normal brain." (PMID 21060868, 2010).
invasive carcinoma (2 papers, 2006 to 2019). A carcinoma that is not confined to the epithelium, and has spread to the surrounding stroma. "As observed with N-cadherin, expression of mesenchymal OB-cadherin (Osteoblast cadherin/cadherin-11/CDH11) is associated with EMT and tumor progression, and is typically found in poorly differentiated and invasive carcinomas with poor prognosis." (PMID 30895176, 2019). "For three of them (cadherin 11, annexin A1, and vimentin), we observe the same expression pattern as published by Nagaraja and colleagues for the transition from in situ to invasive carcinoma." (PMID 17069663, 2006).
keloid (2 papers, 2019 to 2022). An irregularly shaped, elevated mark on the skin caused by deposits of excessive amounts of collagen during wound healing. "Although CDH1 gene expression levels are similar between normal and keloid keratinocytes, keloids express decreased protein levels of E-cadherin, in line with cadherin switching from E-cadherin to mesenchymal markers such as N-cadherin, fibronectin-1, vimentin, and cadherin-11." (PMID 31440236, 2019).
keratoconus (2 papers, 2016 to 2023). A degenerative, structural disorder of the eye, characterized by a cone-shaped protrusion of the cornea. "For instance, several cadherin-family proteins, such as cadherin 11 and desmoglein 1, are known biomarkers for keratoconus, and N-cadherin is critical for corneal epithelial cell maturation." (PMID 37561511, 2023).
metastatic tumors (2 papers, 2019 to 2022). "In addition, ex vivo, we compared the CDH11 expression between the primary and metastatic tumors from the xenograft mice." (PMID 31248373, 2019).
myocardial infarction (2 papers, 2019 to 2023). Gross necrosis of the myocardium, as a result of interruption of the blood supply to the area, as in coronary thrombosis. "Cdh11 has been implicated in autoimmune disorders, aortic valve calcification, and recently, scarring following myocardial infarction through its effect on fibrosis and inflammation." (PMID 37944753, 2023). "A recent study found that CDH11 contributed to inflammation-driven fibrotic remodeling after myocardial infarction, which indicated that the increased CDH11 might be involved in the development of HF through inflammatory response." (PMID 31921308, 2019).
Obesity (2 papers, 2023). Accumulation of substantial excess body fat. "Furthermore, in adipose tissue fibroblasts, CDH11 deficiency reduced their production of ColIII and ColVI, resulting in substantially less adipose tissue fibrosis in obesity." (PMID 36980183, 2023).
osteoporosis (2 papers, 2013 to 2024). A condition of reduced bone mass, with decreased cortical thickness and a decrease in the number and size of the trabeculae of cancellous bone (but normal chemical composition), resulting in increased fracture incidence. "By clustering annotation of human osteoporosis single-cell datasets, we manually annotated only the osteoclast clusters using markers CDH11 and COL1A1, dividing the data into osteoclast and non-osteoclast clusters." (PMID 38883609, 2024).
aneurysm (1 paper, 2022). Bulging or ballooning in an area of an artery secondary to arterial wall weakening. "In our other dataset (GSE54083), we were surprised to find that the expression of CDH11, SPARC, FN1, and FSTL1 in unruptured aneurysms was significantly increased, while WNT11, PCDH9, and GPC3 expression levels were relatively low." (PMID 34997174, 2022). "It was found that the expression levels of CDH11, SPARC, FN1, and FSTL1 genes in unruptured aneurysms were higher than those in healthy samples, while the expression levels of WNT11, PCDH9, and GPC3 in unruptured aneurysms were lower than those in healthy samples." (PMID 34997174, 2022).
aneurysmal diseases (1 paper, 2021). "However, the functions and mechanisms of both CDH8 and CDH11 in aneurysmal diseases have not been clarified." (PMID 33531038, 2021).
aortic stenosis (1 paper, 2023). Aortic valve stenosis is a aortic valve disease caused by the incomplete opening of the aortic valve. "Both celecoxib and dimethyl celecoxib (DMC), a celecoxib derivative with action against CDH11 but no inhibitory effects on COX-2, were investigated as potential therapeutics for the treatment of aortic stenosis." (PMID 37048799, 2023).
aortic valve disease (1 paper, 2017). "In aortic valve disease and development cell junction protein cadherin-11 (Cad-11) has been implicated in a variety of mechano-active defects and similar mechanisms may be at play in MVD." (PMID 29312958, 2017).
asthma (1 paper, 2024). "The 15 most significant DEGs included genes known to play a role in wound healing (FN1, CDH11), immune response (VSIG4, HS3ST4), and asthma drug response (PTHHD4, SPTBN1, FKBP5)." (PMID 38806494, 2024).